CASP8 (caspase 8)
Diseases named in the same sentence as CASP8 in open-access papers (continued):
Sharing a sentence is not in itself a finding about the gene and the disease.
Stroke (17 papers, 2015 to 2025). Sudden impairment of blood flow to a part of the brain due to occlusion or rupture of an artery to the brain. "Oxidative stress and inflammation are associated with the late phase of stroke, leading to the activation of CASP8 and increased CASP8 activity levels, whereas BDNF levels remain low73,74." (PMID 40133606, 2025). "Oxidative stress induced by H2O2 treatment, which mimics molecular changes linked with stroke or high blood pressure, increases levels of CASP8 polyGR+ proteins in transfected SH-SY5Y cells." (PMID 41204969, 2025). "Consistent with this hypothesis, we show that oxidative stress, which can be induced by stroke or high blood pressure, causes increased levels of CASP8 polyGR+ proteins in transfected cells." (PMID 41204969, 2025). "Apoptotic cell death associated with transcriptional elevated levels of CASP8 has been reported in various neurodegenerative diseases, including Alzheimer’s disease (AD), Parkinson’s disease (PD), and stroke." (PMID 31680804, 2019). "Male MMP-3 KO stroke brains also exhibited downregulation of apoptosis-related genes such as Casp9, Casp7, Bmf, Casp1, Bid, Casp6, Casp3, Casp2, Fas, Casp4, and Casp8." (PMID 39000490, 2024). "The volcano plot indicates significant downregulation of genes already implicated in inflammation and apoptotic cell death following stroke such as Ccr5, Casp8, Icam2, Mmp9, Pecam1, and Il6." (PMID 39000490, 2024). "TNF-α secreted by microglia can directly act on TNFR1 on neurons and strongly trigger neuronal death by activating caspase-8 signaling after stroke." (PMID 37486903, 2023). "Mitochondrial ROS influence the release of cytochrome c and other apoptotic proteins (such as caspase-3, caspase-8, and calpain-1) from the mitochondria into the neuronal cytosol, which leads to apoptosis after stroke." (PMID 33656055, 2021). "The cleaved Caspase-8 peaked slightly at day 5 after stroke (Sh: 1.00 ± 0.08; 1 d: 1.08 ± 0.17; 3 d: 1.39 ± 0.26; 5 d: 1.57 ± 0.40; 7 d: 1.18 ± 0.39, P < 0.05), while the level of complete Caspase-8 was also steady." (PMID 33967935, 2021). "For example, we showed that Casp8, Ripk1, and Ripk3 were up-regulated following stroke, although it has been shown that CASP8 blocks assembly of necroptotic complex composed of RIPK1 and RIPK3, leading the cell to apoptosis." (PMID 30394012, 2018). "Analysis of cleaved caspase-8 and -3 expressions in a panel of human stroke cases arranged upon days-after stroke and age-matched controls suggested that the expression of these caspases correlated with the time of onset of stroke." (PMID 27566702, 2016). "In conclusion, we revealed the temporal and spatial activation of caspase-8 and -3 in microglia/macrophages occurring upon ischemic stroke in human stroke subjects and in a mouse model of ischemic stroke." (PMID 27566702, 2016). "Positivity for cleaved caspase-8 was detected in the ischemic core and the peri-infarct area and could be associated with the Iba1-positive cells, as illustrated with immunofluorescence double staining confirming expression of cleaved caspase-8 in Iba1-positive cells upon stroke." (PMID 27566702, 2016). "The multifaceted roles of caspase-8 make this caspase very attractive in the context of future stroke strategies aimed at minimizing brain injury." (PMID 27566702, 2016). "Positive signal for cleaved caspase-8 was detected in numerous cells in the stroke peri-infarct area, as well as some positivity in the ischemic core." (PMID 27566702, 2016). "Furthermore, deregulated activation of caspase-2, caspase-3, and caspase-8 contributes to the exacerbation of liver disease injury, while caspase-1, caspase-3, and caspase-6 knockout protect against stroke." (PMID 39625520, 2024). "It has been reported that it was Caspase-8 that played a decisive role in multiple sclerosis, whereas our data suggested that it was Caspase-1/-11 that represented the primary executors in post-stroke inflammasome activation." (PMID 33967935, 2021).
Stroke (continued). "Ripk1 and Casp8 expression in the ipsilateral hemisphere followed the same pattern: they were significantly up-regulated by stroke (P < 0.01 for Ripk1 and P < 0.001 for Casp8) and reduced by NSC transplantation and the injection of proliferation-supporting medium to levels similar to healthy mice." (PMID 30394012, 2018). "In the human stroke subjects, highest levels of active caspase-8 and active caspase-3 could be detected the first day after the stroke, and then slowly decreases with time until complete disappearance after 5–29 days after the ischemic event." (PMID 27566702, 2016). "We were then interested to examine if activation of the apical caspase-8 and its downstream target caspase-3 could also be detected in MMs in human subjects who had suffered a stroke." (PMID 27566702, 2016). "Analysis of post-mortem brain tissue from human subject who suffered two stroke events, referred as recent and old stroke, revealed that expression of cleaved caspase-8 and -3 in CD68-positive cells could only be found in the recent stroke area." (PMID 27566702, 2016). "Casp8 expression was reduced by both NSC transplantation and the injection of proliferation-supporting medium when compared with healthy and stroke-affected group." (PMID 30394012, 2018). "In fact, confocal imaging demonstrated the presence of both cleaved caspase-8 and cleaved caspase-3 in the cytoplasm of CD68-positive cells, confirming the activation for those caspases in the MMs upon stroke." (PMID 27566702, 2016). "Other examples include CASP8 with cancer, NFKB2 with IBD, and DLG4 with stroke." (PMID 33990562, 2021).
medulloblastoma (16 papers, 2009 to 2023). A malignant, invasive embryonal neoplasm arising from the cerebellum. "Loss of CASP8 protein expression is associated with a poor prognosis in children with medulloblastoma." (PMID 31967976, 2020). "IFNγ-mediated caspase 8 upregulation was also shown to enhance sensitivity of medulloblastoma cells to standard chemotherapeutic agents including cisplatin, doxorubicin, and etoposide, as well as to ionising radiation." (PMID 35568716, 2022). "Weak caspase 8 expression is predictive of unfavourable progression-free survival (PFS) in medulloblastoma, where patients with low caspase 8 tumour levels had a 5-year PFS of 31%, compared with 73% in those with moderate or strong expression." (PMID 35568716, 2022). "Hypermethylation of antioncogene promotors, such as Hypermethylated-in-Cancer 1 (HIC1), ras association domain family 1 isoform A (RASSF1a), and caspase 8 (CASP8), occurs in medulloblastoma." (PMID 34066495, 2021). "For instance, the caspase-8 gene was found methylated in 81% of medulloblastomas analyzed." (PMID 24281211, 2010). "Further, we also demonstrated that SPARC overexpression increased caspase-3 and caspase-8 activities and enhanced PARP cleavage when compared to mock or an empty vector controls in D283 medulloblastoma cells." (PMID 28435518, 2017).
autoimmune lymphoproliferative syndrome (15 papers, 2014 to 2026). Autoimmune lymphoproliferative syndrome (ALPS) is a rare, inherited disorder characterized by non-malignant lymphoproliferation, multilineage cytopenias, and a lifelong increased risk of Hodgkin's and non-Hodgkin's lymphoma. "A full decade before MLKL's role in cell death was discovered, inherited deficiency of Caspase 8 was reported to mediate autoimmune lymphoproliferative syndrome (ALPS)." (PMID 35166320, 2022). "One of the rarest autoimmune lymphoproliferative syndromes is caspase-8 deficiency." (PMID 37038193, 2023). "Caspase-8 enzyme deficiency (CED) is a rare autosomal recessive inborn error of immunity with autoimmune lymphoproliferative syndromes (ALPS), deficient extrinsic apoptosis and hyperactivation of the mammalian target of rapamycin (mTOR) pathway." (PMID 41026346, 2025). "We demonstrate that our patient with CIDP has phenotypic characteristics of the autoimmune lymphoproliferative syndrome (ALPS) due to caspase-8 enzyme deficiency (ALPS-CED)." (PMID 41026346, 2025). "Caspase-8 deficiency is an autosomal recessive subtype of the broad-spectrum autoimmune lymphoproliferative syndrome (ALPS)." (PMID 37038193, 2023). "Furthermore, patients with autoimmune lymphoproliferative syndrome (ALPS) have been shown to carry somatic or germline mutations in the genes that encode FAS, Fas-ligand, caspase 10, caspase 8, NRAS, and KRAS." (PMID 32121251, 2020). "Three patients —one with caspase-8 deficiency and two with BTK gene mutations—were subsequently diagnosed with autoimmune lymphoproliferative syndrome (ALPS) or reactive lymphadenopathy with BMF and were excluded from the analysis." (PMID 40047910, 2025). "Casp8−/−Ripk3−/− and Casp8−/−Mlkl−/− mice, characterized by splenomegaly with a marked accumulation of CD3+CD4−CD8−B220+ T cells, resemble the deficiency of FAS ligand (FasL, CD95L) or FAS (CD95) in mice or the autoimmune lymphoproliferative syndrome (ALPS) in humans." (PMID 35064213, 2022). "Autoimmune lymphoproliferative syndrome (ALPS), characterized by chronic lymphoproliferation, autoimmune manifestations, and an increased lymphoma risk, stems from defects in lymphocyte apoptosis, particularly in components of the apoptotic pathway (e.g., FAS, FASL, FADD, CASP10, and CASP8)." (PMID 38535602, 2024). "Recent studies have shown that the absence of RIPK3 along with either Caspase 8 or FADD caused a lymphoproliferative phenotype in B6 mice, similar to the lymphoproliferation found in Autoimmune Lymphoproliferative Syndrome." (PMID 27669412, 2016). "The Mendelian disease autoimmune lymphoproliferative syndrome (ALPS) arises from defects in the genes FAS, CASP8, and CASP10, which coordinate the Fas-dependent apoptosis that is critical for thymocyte development." (PMID 38589365, 2024).
Immunodeficiency (15 papers, 2016 to 2025). Failure of the immune system to protect the body adequately from infection, due to the absence or insufficiency of some component process or substance. "Caspase-8 knockout mice die during embryonic development from excessive necroptosis, and human caspase-8 mutations are associated with immunodeficiency and inflammatory bowel disease." (PMID 37150321, 2023). "Humans with an inherited deficiency of caspase-8 have shown immunodeficiency with defects in the activation of lymphocytes, including T, B, and NK cells." (PMID 33805003, 2021). "These individuals showed defects in the activation of their T, B lymphocytes, and natural killer (NK) cells proving that Caspase-8 deficiency in humans is compatible with normal development, differently from mice, but it leads to immunodeficiency." (PMID 30501030, 2018). "On the other hand, caspase-8 mutation causes lymphoproliferative disorder and immunodeficiency in people, and reduced caspase-8 expression is associated with atopic dermatitis and epidermal wound responses." (PMID 26757916, 2016). "Furthermore, we recently reported that human OSCCs with low activity of Caspase-8 have apoptotic tumor infiltrating lymphocytes, in line with reports that CASP8 mutations lead to human immunodeficiency." (PMID 39625985, 2024). "In addition, caspase-8 has been implicated in diseases such as lymphoproliferation, immunodeficiency, and autoimmunity in humans." (PMID 35064213, 2022). "Besides, caspase-8 mutation in humans causes immunodeficiency in addition to ALPS, which can be explained by the mechanisms that caspase-8 cleaves and inactivates a cytokine production suppressor NEDD4-binding protein 1 (N4BP1)." (PMID 35064213, 2022). "In human T cells, caspase-8 serves as a link for the CARMA1-Bcl10-MALT1 (mucosa-associated lymphatic tissue) (CBM) and IKK complex to induce NF-κB activation, and an inherited genetic deficiency of caspase-8 in human leads to immunodeficiency by impaired activation of T, B, and NK cells." (PMID 33805003, 2021). "In addition, mutations of Casp8 in lymphocytes also lead to human immunodeficiency, thereby causing dysfunction of the innate immune system, but the roles of Casp8 in antitumor immunity remain unclear." (PMID 33934451, 2021). "Moreover, caspase-8 deficiency is associated with defects in B and T cell activation and immunodeficiency whereas caspase-10 deficiency is associated with susceptibility to infections and arthritis, pointing to a dual role of caspases in inducing both apoptotic and non-apoptotic signaling." (PMID 31114586, 2019). "Consistently, it has been shown that selective impairment of caspase-8 expression in T-cells leads to immunodeficiency in mice and humans as well." (PMID 35853963, 2022). "Consistently, additional studies have shown that selective impairment of Caspase-8 expression in T-cells in mice leads to immunodeficiency as well." (PMID 30501030, 2018). "Patients with ALPS-CED not only suffer from ALPS but also present with an immune deficiency and a chronic inflammatory state both related to non-apoptotic functions of caspase-8." (PMID 41026346, 2025). "In addition, CASP-8 is involved in a variety of inflammatory diseases, including immune system disorders and cancer." (PMID 40563617, 2025). "Besides the patient mutations of the regulatory caspase 8 cleavage site in RIPK1 (D324A/E/H) we integrated the C601Y missense mutation, which causes immunodeficiency and inflammatory bowel disease, into the reporter." (PMID 39088265, 2024). "The role of caspase-8, RIPK3, and MLKL in non-programmed cell death has been reported to regulate lymphadenopathy, lymphoproliferation and immunodeficiency." (PMID 35064213, 2022).
inflammatory bowel disease (15 papers, 2019 to 2025). A spectrum of small and large bowel inflammatory diseases of unknown etiology. "Studies have shown that patients with inflammatory bowel disease characterized by hereditary Casp8 deficiency exhibit T lymphocyte dysfunction." (PMID 40308566, 2025). "Caspase-8 deficiency manifests as very early-onset Inflammatory Bowel Disease (VEO-IBD) in some individuals." (PMID 35166320, 2022). "However, caspase-8 mutations in humans have also been linked to inflammatory bowel disease (IBD) and multi-organ lymphocytic infiltration with granulomas, and the precise mechanisms underlying this relationship remain elusive." (PMID 35064213, 2022). "In addition, homozygous mutations in the CASP8 gene leading to caspase-8 deficiency and increased necroptosis have been described in patients with very early onset inflammatory bowel disease (VEO-IBD)." (PMID 36578489, 2022). "Indeed, in both cultures, we observed a sharp increase in Mixed Lineage Kinase Domain Like Pseudokinase (MLKL) mRNA levels, which is known to be associated with Caspase 8 deficiency and Inflammatory Bowel Disease commonly observed in patients." (PMID 34608167, 2021). "Strikingly, CASPASE 8-deficiency was also found to cause very early-onset inflammatory bowel disease (VEO-IBD)." (PMID 34434197, 2021). "Patients with inflammatory bowel disease (IBD) with inherited Casp8 deficiency also exhibit T cell and B cell dysfunction." (PMID 33934451, 2021). "He represented very early-onset inflammatory bowel disease (IBD) and was diagnosed with the caspase-8 deficiency." (PMID 37038193, 2023). "Necroptosis was shown to be active in humans with inflammatory bowel disease, where Caspase-8 was reduced and RIP3, thought to be a key mediator in necroptotic processes, increased." (PMID 31760064, 2020). "Interestingly, while caspase-8 deficiency is embryonically lethal in mice, it is not in humans but can lead to severe clinical presentations, including immunodeficiency and very early-onset inflammatory bowel disease (IBD)." (PMID 39996713, 2025). "Furthermore, we present robust protocols for detecting human Caspase-8, RIPK1, RIPK3, and MLKL and illustrate their utility for detecting dysregulated necroptosis in biopsies from patients with inflammatory bowel disease (IBD)." (PMID 38750308, 2024).
Lymphadenopathy (15 papers, 2015 to 2025). Enlargement (swelling) of a lymph node. "Splenomegaly in Casp8−/−Tnfr1−/−Trif−/−Zbp1−/− mice reflected extramedullary hematopoiesis rather than an accumulation of B220+CD3+ T cells, the latter underlying splenomegaly and lymphadenopathy in older Casp8−/−Ripk3−/− or Casp8−/−Mlkl−/− mice." (PMID 38548850, 2024). "Double deficient mice of caspase-8 and Mlkl genes, Casp8−/−; Mlkl−/− mice, were normal but showed pronounced splenomegaly, thrombocytopenia, and lymphadenopathy after a few months of age." (PMID 26491219, 2015). "Due to the splenomegaly and lymphadenopathy that occurs in Casp8−/−; Mlkl−/− and Casp8−/−; Ripk3−/− mice, they were sacrificed once endpoint criteria were reached and skin samples were collected for immunohistochemical analysis." (PMID 38783091, 2024). "As expected, Ripk1K376R/K376RCasp8−/−Ripk3−/− and Ripk1+/+Casp8−/−Ripk3−/− mice developed the lymphadenopathy that is associated with caspase-8 deficiency and therefore were not aged beyond 11–13 weeks." (PMID 32999468, 2021). "For instance, rare mutations in RIPK1, such as D324N, D324H, and D324Y at the Caspase-8 recognition site LQLD, block Caspase-8-mediated cleavage of RIPK1, resulting in an autosomal-dominant autoinflammatory disease, characterized by recurrent fevers and lymphadenopathy." (PMID 39062098, 2024). "Indeed, the lethality of Ripk1D325A/D325ACasp8−/− embryos can be rescued by Mlkl−/− to adulthood, similar to Casp8−/− embryos, and the resulting Ripk1D325A/D325ACasp8−/−Mlkl−/− mice exhibited similar lpr phenotypes (lymphadenopathy and splenomegaly) to those of Casp8−/−Mlkl−/− mice." (PMID 34437534, 2021). "A nomogram based on the most predictive clinical variables (age, Tis (in situ), gender, history of NMIBC, and lymphadenopathy) and genes selected following the Akaike information criterion (AIC) (CBTB16, CHMP6, DDX54, CASP8, LOR, and PLEC) was then created." (PMID 40149716, 2025). "Interestingly, caspase-8−/−/RIPK3−/− or caspase-8−/−/MLKL−/− double-ko mice develop hyperinflammation and lymphadenopathy, a phenotype resembling that observed in CD95-deficiency Lpr mice strongly suggesting that these factors control an additional mechanism in which CD95 could be involved too." (PMID 35563744, 2022). "Finally, the deficiency of caspase-8 may be also considered in the differential diagnosis of CRIA syndrome, because both diseases share some pathophysiological mechanisms (partial or total impairment of normal caspase-8 function) and clinical features such as lymphadenopathies and splenomegaly." (PMID 35716229, 2022). "Unfortunately, we were unable to age these mice more than 15 weeks, as they developed lymphadenopathy, and we could therefore not examine the effect of Mlkl-/-Casp8-/- on the late onset inflammation in the skin." (PMID 26701909, 2015).